LAMB1 (laminin subunit beta 1)
Diseases named in the same sentence as LAMB1 in open-access papers (continued):
Sharing a sentence is not in itself a finding about the gene and the disease.
glioblastoma (4 papers, 2009 to 2022). The most malignant astrocytic tumor (WHO grade IV). "At the time of writing this manuscript, LAMB1 was claimed as a key survival biomarker in mesenchymal glioblastoma." (PMID 35806337, 2022). "Plus, LAMB1 serves as a target of miR-124-5p in glioblastoma multiforme (GBM)." (PMID 36299585, 2022). "Our functional enrichment of genes in patient tumors revealed that low expression of RND1 in glioblastoma induces an overexpression of focal adhesion proteins like extracellular matrix proteins (COL1A1 and LAMB1); integrins (ITGA5 and ITGB1); actin-binding proteins (FLNA; ACTN1) and vinculin." (PMID 30333910, 2018).
liver fibrosis (4 papers, 2012 to 2024). "In a recent multi-transcriptome analysis, COL4A2 and LAMB1 were identified as prioritized genes specifically associated with liver fibrosis progression, independent of etiology." (PMID 39585303, 2024). "In addition, the Lamb1 and Lama1 genes are related to the progression of liver fibrosis." (PMID 39591294, 2024).
Obesity (4 papers, 2020 to 2025). Accumulation of substantial excess body fat. "Associated with adipogenesis and obesity, LAMB1 is highly expressed during the mid-stage of adipogenesis." (PMID 40130165, 2025). "Similar to LAMA4 and LAMB1, LAMC1 is closely related to adipogenic differentiation, with significant overexpression in obesity-associated samples." (PMID 40130165, 2025). "Obesity alters the gene expression profile of ECM genes in adipose tissue (LAMB1 was upregulated in visceral and subcutaneous adipose tissue)." (PMID 34956370, 2021). "When the effect of obesity was studied, the expression of LAMB1, Serpine1, MMP14, MMP10 appeared to decrease but a general downward trend could be noted." (PMID 33505957, 2020).
ovarian carcinoma (4 papers, 2020 to 2023). A malignant neoplasm originating from the surface ovarian epithelium. "LAMB1 has been identified in the EMT process of chemoresistant ovarian cancer cell lines, contributing to a more invasive phenotype." (PMID 38031074, 2023). "Overexpression of LAMA4, LAMB1, and LAMC1 mRNAs has been associated with lower overall survival (OS) and progression-free survival (PFS) in ovarian cancer." (PMID 38031074, 2023). "The laminin family members LAMA5, LAMB1, and LAMC1 were the most prominently upregulated proteins in LV-ETS1 Exos of the two ovarian cancer cell lines." (PMID 36477408, 2022). "In a survival analysis of patients with ovarian cancer in the GSE9891 dataset, increased expression of LAMA5, LAMB1, and LAMC1 was related to shorter overall survival." (PMID 36477408, 2022). "ETS1 overexpression altered the size of exosomes derived from ovarian cancer cells, and upregulated the expression of three laminins, LAMA5, LAMB1, and LAMC1, in ovarian cancer cells and their exosomes." (PMID 36477408, 2022). "In ovarian cancer samples from the TCGA database, the expression levels of LAMA5, LAMB1, and LAMC1 were positively correlated with that of ETS1." (PMID 36477408, 2022). "According to qRT-PCR and western blotting data, ETS1 regulated the expression of LAMA5, LAMB1, and LAMC1 in ovarian cancer cells." (PMID 36477408, 2022). "The results show that ETS1 transcriptionally regulates the expression of LAMA5, LAMB1, and LAMC1 in ovarian cancer cells." (PMID 36477408, 2022).
prostate carcinoma (4 papers, 2009 to 2024). A carcinoma that arises from epithelial cells of the prostate gland. "LAMB1 plays a role in the movement and infiltration of cells into the adjacent extracellular matrix in prostate cancer." (PMID 38239636, 2023). "In prostate cancer, LAMB1 was shown to be involved in cell motility and invasion into the surrounding ECM." (PMID 32581652, 2020). "All ligands except LAMB1 were downregulated, suggesting that suppression of integrin ligands plays a role in the initiation of prostate cancer." (PMID 19653896, 2009).
cobblestone lissencephaly (3 papers, 2020 to 2024). "Mutations in Laminin beta-1 (LAMB1) lead to cobblestone-lissencephaly in patients, caused by over-migration of neurons upon detachment of the basal endfeet of RG." (PMID 39416687, 2024). "Laminins are critical for the structural integrity of the basement membrane, and patients with mutations in Laminin beta-1 (LAMB1) develop cobblestone-lissencephaly." (PMID 33344456, 2020).
liver cancer (3 papers, 2021 to 2025). An epithelial or non-epithelial malignant neoplasm that arises from the liver. "In early-stage of liver cancer, elevated LAMB1 mediated the increased secretion of laminin 111 (Ln-111)." (PMID 33435161, 2021).
lung adenocarcinoma (3 papers, 2021 to 2024). A carcinoma that arises from the lung and is characterized by the presence of malignant glandular epithelial cells. "The WB results indicate that the expression of the LAMB1 protein is down-regulated in human lung adenocarcinoma cell lines A549, H1299, H1975, HCC78, and PC9 compared to normal bronchial epithelial cells (BEAS-2B)." (PMID 39312319, 2024). "The expression of the LAMB1 gene was analyzed in 5 human lung adenocarcinoma cell lines using Western blotting." (PMID 39312319, 2024).
atherosclerosis (2 papers, 2014 to 2021). A disease characterized by the build-up of fatty material and calcium deposition in the arterial wall resulting in partial or complete occlusion of the arterial lumen. "Whether the rest of them, including Dkk2, Ltbp2, Lamb1, Cdca7l, Dclk1, and Slc45a4, are associated with atherosclerosis and d-flow has not been reported." (PMID 34282126, 2021).
COVID-19 (2 papers, 2023). A disease caused by infection with severe acute respiratory syndrome coronavirus 2. "The most changed components of BM included laminins (LAMB2, LAMA2, LAMC3, LAMB1, LAMC1, and LAMA5) and proteoglycans (COL18A1, HSPG2, and AGRN), with some BM specific collagens (IV, VIII, XVIII, and V collagens) remaining in COVID-19 brains, as compared with the control brains." (PMID 36609561, 2023).
human papillomavirus infection (2 papers, 2024). "The upregulated genes (n = 135) included ATM, COL1A1, FN1, ITGA6, and LAMB1, which were found to be enriched in pathways related to human papillomavirus infection and herpes simplex virus 1 infection." (PMID 40226717, 2024).
Hydrocephalus (2 papers, 2015 to 2021). Hydrocephalus is an active distension of the ventricular system of the brain resulting from inadequate passage of CSF from its point of production within the cerebral ventricles to its point of absorption into the systemic circulation. "Given the high level of mRNA for Lamb1 in choroid plexus of mice, it is of interest that the LAMB1 homozygous COB patients also had hydrocephalus, likely due to impaired ECM structural integrity in the choroid plexus." (PMID 26705335, 2015).
Lissencephaly 5 (2 papers, 2022 to 2023). "The LAMB1 gene is the responsible gene of lissencephaly 5 (OMIM #615191) characterized by focal and spasmodic seizures and psychomotor development delay." (PMID 35663266, 2022).
metastatic cancer (2 papers, 2015 to 2023). A carcinoma which has spread from the original site of growth to another anatomic site. "Results revealed a higher Mesenchymal markers in primary cancer cells (e.g., NCAM1, LAMB1, SERPINE1, TCF4, VIM, ZEB1, and ZEB2) and a higher Epithelial markers in metastatic cancer cells (e.g., CDH1, CLDN4, ELF3, EPCAM, KRT18, KRT7, and KRT8)." (PMID 37202394, 2023).
multiple myeloma (2 papers, 2020 to 2021). "However, there is rare research on the role which ITGA9 and LAMB1 play in myeloma development and metastasis." (PMID 32581652, 2020). "Therefore, LAMB1 which may be regulated by HIF-1 played a vital role in myeloma cell adhesion." (PMID 32581652, 2020).
Alpha-thalassemia (1 paper, 2022). Alpha-thalassemia is an inherited hemoglobinopathy characterized by impaired synthesis of alpha-globin chains leading to a variable clinical picture depending on the number of affected alleles. "These genes included laminin subunit beta 1(LAMB1), ATPase Na+/K+ transporting subunit alpha 1 (ATP1A1), alpha thalassemia/mental retardation syndrome X-linked (ATRX), and methyl-CpG binding domain protein 1 (MBD1)." (PMID 36389237, 2022).
amoebiasis (1 paper, 2024). "Within the biological process of amoebiasis, dietary supplementation with PPAH decreased the expression of several genes, including Il6, Serpinb9c, Rab5a, Muc2, Rab7, Lamb1, and Lama1." (PMID 39591294, 2024).
Anxiety (1 paper, 2024). Intense feelings of nervousness, tension, or panic often arise in response to interpersonal stresses. "Furthermore, loss of LAMB1 in the anterior cingulate cortex was found to increase pain sensitivity and be associated with anxiety- and depressive-like behavior in mice." (PMID 38267423, 2024).
asthma (1 paper, 2022). "The highly expressed stromal marker genes like KDR and LAMB1 in mesenchymal cells also indicated the presence of stromal cells in the mesenchyme following an asthma attack." (PMID 36439114, 2022). "We compared the differential genes of 4 subtypes of cells after the asthma attack and found highly variable genes in MC1 were concentrated in biological processes, including cell migration and proliferation, which were also widely expressed in epithelial cells (e.g., KDR and LAMB1)." (PMID 36439114, 2022).
autism (1 paper, 2024). Persistent deficits in social interaction and communication and interaction as well as a markedly restricted repertoire of activity and interest as well as repetitive patterns of behavior. "A polymorphism in LAMB1 gene has been earlier associated with autism severity, neural development of embryonic stem cells and pain sensitivity in mice." (PMID 38267423, 2024).
autosomal recessive deafness (1 paper, 2022). "Laminin subunit beta (LAMB1) may be a candidate gene (differentially expressed by > 1,5-fold) in patients suffering from DFNB14, which accounts for non-syndromic human autosomal recessive deafness, for which no causative gene has been identified to date." (PMID 35573665, 2022).
benign prostatic hyperplasia (1 paper, 2024). A non-cancerous nodular enlargement of the prostate gland. "Results showed that the plasma sEV protein LAMB1 had significantly higher expression levels in the metastatic group of PCa patients compared to the high‐risk and control groups [healthy and benign prostatic hyperplasia (BPH) participants]." (PMID 38590132, 2024).
bladder cancer (1 paper, 2025). "Although Excretion‐EVs did not directly induce drug resistance in recipient bladder cancer cells, their selective enrichment in regulatory proteins, such as H3.2 (H3C14), LAMB1 and CD147, suggests an indirect role in maintaining chemoresistance." (PMID 41159684, 2025).
brain malformation (1 paper, 2015). "LAMB1, encoding the laminin subunit beta-1 is involved in basal process attachment to the pial surface and also found mutated in a cobblestone brain malformation." (PMID 25729350, 2015).
Cirrhosis (1 paper, 2020). A chronic disorder of the liver in which liver tissue becomes scarred and is partially replaced by regenerative nodules and fibrotic tissue resulting in loss of liver function. "Similarly, LSECs isolated from livers of rats with cirrhosis and cultured on low stiffness (0.5 kPa) exhibited a decreased expression of the capillarisation marker Lamb1." (PMID 32939447, 2020).
congenital hydrocephalus (1 paper, 2021). Hydrocephalus that is present at birth. "LAMB1, MPDZ were analyzed because the mutations in either are known to be associated with congenital hydrocephalus with autosomal recessive genetic inheritance." (PMID 33854687, 2021).
cryptorchidism (1 paper, 2021). The failure of one or both testes of a male fetus to descend from the abdomen into the scrotum during the late part of pregnancy. "C481F in another Laminin EGF-like domain is a deleterious mutation affecting protein function, and a mutation in LAMB1 (I1620T) has been reported in a male infant diagnosed with hydranencephaly along with cryptorchidism." (PMID 34702182, 2021).
cutaneous melanoma (1 paper, 2020). A primary melanoma arising from atypical melanocytes in the skin. "Here, LAMA1 and LAMB1 have been identified as potential markers for cutaneous melanoma metastasis as these proteins are involved in the modulation of cell adhesion and migration." (PMID 32886718, 2020).
diabetic nephropathy (1 paper, 2024). "Increased expression of LAMB1 is observed in response to kidney inflammation and serves as a biomarker for diabetic nephropathy, indicating its relevance to kidney injury and repair." (PMID 39519211, 2024).
dilated cardiomyopathy (1 paper, 2020). Cardiomyopathy which is characterized by dilation and contractile dysfunction of the left and right ventricles. "Coding exons of LAMB1, LAMB4 and PIK3CG were screened in dilated cardiomyopathy." (PMID 33041871, 2020).
endometriosis (1 paper, 2021). The growth of functional endometrial tissue in anatomic sites outside the uterine body. "The results of phenolyzer analysis showed that ITGB1, HDAC2 and LAMB1 were the top three important genes in endometriosis." (PMID 34586697, 2021).
epilepsy (1 paper, 2022). A brain disorder characterized by episodes of abnormally increased neuronal discharge resulting in transient episodes of sensory or motor neurological dysfunction, or psychic dysfunction. "Structurally, the laminin subunit α5 forms heterotrimers with laminin subunits β1/β2 and γ1/γ3, which were encoded by LAMB1, LAMB2, LAMC1, and LAMC3 that were associated with neurodevelopmental diseases and epilepsy." (PMID 35663266, 2022).
Fuchs endothelial corneal dystrophy (1 paper, 2024). Fuchs endothelial corneal dystrophy (FECD) is the most frequent form of posterior corneal dystrophy (see this term) and is characterized by excrescences on a thickened Descemet membrane (corneal guttae), generalized corneal edema, with gradually decreased visual acuity. "A multi-ancestry GWAS meta-analysis of Fuchs endothelial corneal dystrophy identifies eight novel loci, including low-frequency missense variants in laminin genes LAMA5 and LAMB1, and phenome-wide scans uncover pleiotropy with renal traits at TCF4." (PMID 38582945, 2024).
gastric tumors (1 paper, 2025). "LAMB1, also known as Laminin β1, has been found to be highly expressed in invasive gastric tumors." (PMID 39866228, 2025).
graft-vs-host disease (1 paper, 2019). "Further increased deposition of LAMB1 is occurring, laminin β1 has been shown to be increased in a model of graft-vs-host disease in early disease but then reduces as disease progresses, increased laminin deposition was also seen in two of five human LN biopsies." (PMID 31807119, 2019).
IgA nephropathy (1 paper, 2023). "For example, IgA nephropathy (IgAN), which is one of the most prevalent chronic glomerular diseases, had significantly more matrisome proteins (Col4a1, Lamb1, Hspg2, Emilin, Fgg and Fbln) in diseased patients compared to healthy patients." (PMID 36769148, 2023).
Infertility (1 paper, 2025). "Also, menstrual blood serum was characterized as a less invasive source of infertility biomarkers, where EMILIN1, TRIP6, LAMB1, LAMC1, NID1, APOB, APOA4 were detected as the main differences in uIF patients as compared to healthy controls." (PMID 40861859, 2025).
ischemic stroke (1 paper, 2022). A stroke disorder caused by obstruction of blood flow to the brain, due to thrombotic (local blood clot formation) or embolic (due to a blood clot or other material traveling from another site) event. "Many of the identified genes, including TLR2, TLR3, TLR9, GRN, COL1A1, FN1, and LAMB1, were reported as upregulated genes in previous reports of ischemic stroke." (PMID 35887140, 2022).
limb-girdle muscular dystrophy (1 paper, 2016). Limb-girdle muscular dystrophy (LGMD) is a heterogeneous group of muscular dystrophies characterized by proximal weakness affecting the pelvic and shoulder girdles. "LAMB1 is one of several extracellular matrix glycoproteins and has been previously associated with muscular dystrophies – particularly limb-girdle muscular dystrophy, where LAMB1 levels have been observed to be decreased." (PMID 27549615, 2016).
malaria (1 paper, 2022). Malaria is a serious and sometimes fatal disease caused by a parasite that commonly infects a certain type of mosquito which feeds on humans. "The response of Lamb1 expression to malaria differed from that of Lama1, though there was an almost similar unresponsive phase in unvaccinated mice until day 4 p.i., as also observed for Lama1." (PMID 35214745, 2022).
mesenchymal tumors (1 paper, 2023). "The combination of the expression of the genes PLAU, LAMB1, COL6A1, and TGFBI classified correctly the majority of mesenchymal tumors." (PMID 38031074, 2023).
metastasis (1 paper, 2018). The spread or migration of cancer cells from one part of the body (where they first appeared) to another. "In the RNA sequencing data genes linked to arteries (Elastin, Lamb1, Acta2), pericytes (Cspg4/Ng2, Pdgfrb, Sca1 (Ly6a)) and neurons/neurites (Gap43, Tubb3) were up-regulated in the stroma of osteolytic bone metastasis." (PMID 29988965, 2018).
nasopharyngeal carcinoma (1 paper, 2025). A carcinoma arising from the nasopharyngeal epithelium. "However, the role of LAMB1 in Nasopharyngeal Carcinoma (NPC) remains unknown." (PMID 39874810, 2025).
non-small cell lung carcinoma (1 paper, 2024). A group of at least three distinct histological types of lung cancer, including non-small cell squamous cell carcinoma, adenocarcinoma, and large cell carcinoma. "Thus, LAMB1 could be a potential prognostic molecule in non-small cell lung cancer." (PMID 39312319, 2024).
osteoporosis (1 paper, 2025). A condition of reduced bone mass, with decreased cortical thickness and a decrease in the number and size of the trabeculae of cancellous bone (but normal chemical composition), resulting in increased fracture incidence. "Identifying 8 key genes as potential regulatory target genes for the differentiation of mesenchymal stem cells into osteoblasts or adipocytes under the condition of disuse osteoporosis (ITGB3, LAMC1, COL6A3, ITGA8, PDGFRB, ITGA4, LAMB1, LAMA4)." (PMID 40130165, 2025).
pneumoconiosis (1 paper, 2025). An occupational lung disorder caused by inhalation of dust particles. "Currently, genome-wide association studies (GWAS) have identified a strong association between some common single-nucleotide polymorphisms (SNPs), such as small nucleolar RNA host gene 14 (SNHG14), desmoplakin (DSP), and laminin beta 1 (LAMB1), and pneumoconiosis." (PMID 40182855, 2025).
Rapid-onset dystonia-parkinsonism (1 paper, 2015). Rapid-onset dystonia-parkinsonism (RDP) is a very rare movement disorder, characterized by the abrupt onset of parkinsonism and dystonia, often triggered by physical or psychological stress. "Lamb1 is expressed in several sites implicated in movement disorders, including sites that showed neuropathology in rapid-onset dystonia-parkinsonism (RDP)." (PMID 26705335, 2015).
Rotavirus infection (1 paper, 2025). Infection with any of the rotaviruses. "During rotavirus infection, DARVR adsorbs miR-365-1-5p, alleviating its inhibitory effect on LAMB1." (PMID 40237496, 2025). "Although the RNA interference experiment of LAMB1 seemed to have little effect on the replication of the rotavirus genome, this may be because the infection MOI of rotavirus was too high, and rotavirus infection with a lower MOI may make this experiment biologically meaningful." (PMID 40237496, 2025).
SAPHO syndrome (1 paper, 2019). SAPHO syndrome (acronym for Synovitis, Acne, Pustulosis, Hyperostosis and Osteitis) is an auto-inflammatory disease, mainly characterized by the association of neutrophilic cutaneous involvement and chronic osteomyelitis. "Components of laminin (LAMA4, LAMB1 and LAMC1) and MCAM also help cell adhesion and slow-rolling of neutrophils, the up-regulation of whom indicated excessive neutrophil activation and migration in SAPHO syndrome." (PMID 31395074, 2019).